CFC1 (cryptic, EGF-CFC family member 1)
Description:
NODAL coreceptor involved in the correct establishment of the left-right axis. May play a role in mesoderm and/or neural patterning during gastrulation.
Synonyms: CRYPTIC; DTGA2; HTX2
Tractability: Antibody: UniProt places it where antibodies can reach, with high confidence; UniProt predicts a signal peptide or a membrane-spanning region; its Gene Ontology location is reachable by antibodies, with medium confidence.
Gene: Protein-coding gene on chromosome 2 (130,592,165 to 130,599,575, reverse strand). Ensembl gene ENSG00000136698.
Subcellular location: Cell membrane; Secreted
Pathways (Reactome):
Developmental Biology: Regulation of signaling by NODAL; Signaling by NODAL
Gene Ontology:
Molecular function: nodal binding; activin receptor binding
Biological process: nodal signaling pathway; anterior/posterior pattern specification; blood vessel development; determination of left/right symmetry; heart development; signal transduction
Cellular component: cell surface; extracellular region; plasma membrane
Genetic constraint (gnomAD): Loss-of-function variants: 0 observed, 5.11 expected, observed/expected ratio (o/e) 0, 90% interval 0 to 0.59. That is too few expected variants to judge how well the gene tolerates losing a copy. Missense variants: 9 observed, 38.82 expected, observed/expected ratio (o/e) 0.23, 90% interval 0.14 to 0.41. Synonymous variants: 8 observed, 16.73 expected, observed/expected ratio (o/e) 0.48, 90% interval 0.28 to 0.86.
Homologues: Orthologues: chimpanzee CFC1B (98% identical), macaque CFC1 (69% identical), mouse Cfc1 (45% identical), rat Cfc1 (45% identical), tropical clawed frog tdgf1.2 (26% identical). Paralogues in human: CFC1B (99% identical), CRIPTO (22% identical), CRIPTO3 (22% identical), EGFL7 (17% identical), EGFL8 (14% identical).
Diseases named in the same sentence as CFC1 in open-access papers:
CFC1 is named in the same sentence as 20 diseases in open-access papers, as found by Europe PMC text mining. Sharing a sentence is not in itself a finding about the gene and the disease. The quoted sentences say what the papers report.
situs inversus (2 papers, 2007 to 2022). A congenital condition in which there is complete right-to-left reversal of the position of the major thoracic and abdominal organs (that is, they are arranged in a mirror image of the normal positioning). "Third, the inv mice model with bile duct obstruction and situs inversus with DPM and the findings of mutations in laterality genes (CFC1, ZIC3) in some patients with BA and laterality defects together underlines the role of morphogenetic defects in bile duct malformation." (PMID 35887185, 2022).
asplenia (1 paper, 2018). "The spleen is reduced in mice lacking the NODAL receptor Acvr2b, although asplenia seems to be observed only in Cfc1 (Cryptic) mutants." (PMID 29992973, 2018).
malignant pheochromocytomas (1 paper, 2017). "CFC1 was detected as one of five DEGs that had high diagnostic accuracy associated with malignant pheochromocytomas by genome-wide expression profiling, suggesting CFC1 oncogenic ability in neural crest-related cell lineages." (PMID 28620148, 2017).
Sepsis (1 paper, 2023). Sepsis is defined as life-threatening organ dysfunction caused by a dysregulated host response to infection. "Gene entities exhibiting stronger expression in the SIRS-ranked dataset included CFC1, CT62, lnc-DAAM2-1 and lnc-LTBP3-2 and in the sepsis-ranked dataset included TDRD9, DAAM2, OLFM4 and OLAH." (PMID 38332914, 2023).
spinal muscular atrophy (1 paper, 2025). A motor neuron disease that affect the muscles, and characterized by muscle weakness and atrophy resulting from progressive degeneration and irreversible loss of the anterior horn cells in the spinal cord (i.e., lower motor neurons) and the brain stem nuclei. "This issue concerns regions related to numerous disease-associated genes, such as SMN1 (spinal muscular atrophy) and CFC1 (congenital heart defects)." (PMID 40244459, 2025).
Tetralogy of Fallot (1 paper, 2017). A congenital cardiac malformation comprising pulmonary stenosis, overriding aorta, ventricular septum defect, and right ventricular hypertrophy. "This CFC1 variant was also reported in one subject with sporadic DORV, ventricular septal defect, aortic arch hypoplasia and in a patient with tetralogy of Fallot." (PMID 28738792, 2017).
viral infections (1 paper, 2025). "In clinical diagnostics, genetic testing for CFC1 can aid in identifying the hereditary etiology of visceral heterotaxia and differentiate it from phenotypes caused by teratogenic environmental factors, such as maternal diabetes or viral infections." (PMID 40552176, 2025).
cancer (2 papers, 2017 to 2020). A tumor composed of atypical neoplastic, often pleomorphic cells that invade other tissues. "Expression of CFC1 in adult tissue is associated with various cancers, e.g., pancreatic cancer, colon cancer, and gall bladder cancer." (PMID 33224314, 2020).
tumor (2 papers, 2017 to 2019). "In the quantitative RT-PCR (qPCR) analysis, CFC1 expression normalized by ACTB was also strongly up-regulated in the tumor spheres of all three cell lines." (PMID 28620148, 2017). "The depletion of CFC1 by shRNA significantly suppressed tumor sphere formation in 3 NB cell lines, and xenograft tumor formation in IMR32 cells along with Ki-67 positive signals decreased." (PMID 28620148, 2017). "The expression levels of CDK4, CDKN2A, p14-ARF, and p16-INK4A, a tumor suppressor of NB, were decreased in CFC1-overexpressing cells." (PMID 28620148, 2017). "In order to study the role of EGF-CFC family molecules in NB tumor sphere formation, the expression levels of CFC1, TDGF1, ACVR2A, ACVR2B, and ACVR1B were measured using a microarray." (PMID 28620148, 2017). "Furthermore, tumor sphere formation up-regulated CFC1 transcription in primary tumor spheres and NB cell line spheres, suggesting the epigenetic regulation of CFC1 in NB cells." (PMID 28620148, 2017). "In addition, the functional role of CFC1 in NB tumorosphere formation has been realized and further identified that CFC1 directly targets activin-A induced cell differentiation and Smad phosphorylation, resulting in tumor progression." (PMID 31867574, 2019). "In the three tumor spheres formed from MYCN-amplified NB cell lines, CFC1 and the positive control CD133 were markedly increased and a quantitative PCR analysis confirmed the induction of CFC1." (PMID 28620148, 2017). "This is the first study to clarify the functional role of CFC1 in the Activin signal pathway and suggest the importance of the mechanism suppressing differentiation in NB CSC-model tumor spheres." (PMID 28620148, 2017). "Furthermore, tumor sphere experiments indicated that sb431542 significantly increased sphere formation in NGP cells; the expression of CFC1 also had a significant effect on sphere formation." (PMID 28620148, 2017). "The expression of CFC1 and CD133 was markedly up-regulated in tumor spheres." (PMID 28620148, 2017).
CFC1 also shares sentences with these, for which no sentence is quoted: Alagille syndrome (1 paper); Arthritis (1); bile duct obstruction (1); carcinoid tumor (1); congenital heart malformations of (1); melanoma (1); neuroblastoma (1); polycystic kidney and hepatic disease 1 (1); polycystic kidney disease 2 (1); prostate carcinoma (1); ventricular septal defect (1).